SMARCA4 (SWI/SNF related BAF chromatin remodeling complex subunit ATPase 4)
Diseases named in the same sentence as SMARCA4 in open-access papers (continued):
Sharing a sentence is not in itself a finding about the gene and the disease.
tumor (continued). "Interestingly, SMARCA4 (also known as BRG1) is a transcriptional regulator that can control the activity of Sonic hedgehog and GliA and their downstream targets, providing a driving force for tumor proliferation by activating mitogenic genes such as GLI1, CCND1 and MYC." (PMID 29137349, 2017). "As a tumor suppressor aberrantly expressed in approximately 10% of NSCLC, SMARCA4-DNSCLC exhibits a unique combination of histomorphological, immunophenotypic, and molecular genetic attributes with weak response to conventional chemotherapy and poor prognosis." (PMID 41395620, 2025). "As such, pharmacological inhibition of SWI/SNF ATPases (e.g., SMARCA4/2 inhibitors and BRD9 degraders) disrupts chromatin accessibility at POU2F3 regulatory loci, leading to transcriptional reprogramming and impaired tumor growth." (PMID 40333678, 2025). "Inhibition of the mSW/SNF complex, which specifically targets SMARCA4/2 ATPases and BRD4, has been shown to impede SCLC-P tumor growth." (PMID 41194225, 2025). "Upregulation of epigenetic and transcriptional regulators such as NPM1, SMARCA4, ASPSCR1-TFE3 and TFEB further suggests that tumor signals drive transcriptional reprogramming of model immune cells, creating a stable pro-oncogenic phenotype." (PMID 41514627, 2025). "SMARCA4 is one of the catalytic subunits in SWI/SNIF chromatin remodeling complexes and has recently been suggested as a tumor suppressor." (PMID 38710944, 2025). "Further, treatment with clinical-grade SMARCA4/2 ATPase inhibitors markedly attenuates DDEC cell proliferation and tumor growth in vivo and synergizes with carboplatin-based chemotherapy to extend survival." (PMID 41279405, 2025). "In summary, this study highlights that treatment with SMARCA4 inhibitors enhances the persistence of CD8+ T cells, increases memory phenotypes, and boosts anti-tumor activity." (PMID 40342423, 2025). "The gene expression analysis revealed that several hub genes, such as ETNK1, KDM3A, EZH2, SMARCA4, and CASP3, were significantly overexpressed in HCC tissues, suggesting their potential roles in tumor progression and as biomarkers for HCC." (PMID 40074445, 2025). "Genes downregulated by both agents included those corresponding to stem cell signatures, SMARCA4 target genes, EMT, and MYC targets, tumor invasiveness and TGFB1 signatures." (PMID 41279405, 2025). "SMARCA4 was found to function with BRM and interact with the protein product of the retinoblastoma tumor suppressor gene to inhibit the function of the E2F transcription factor." (PMID 39697230, 2024). "The multivariate analysis was conducted for both carcinoma groups (NKSCC and KSCC) through Pearson correlation studies to evaluate the following variables: tumor size, age, and mosaic expression of SMARCB1 and SMARCA4." (PMID 39590317, 2024). "ACBI-1 is a PROTAC technology-based BAF ATPase subunit SMARCA2 and SMARCA4 degradant, is also a PBAF member PBRM1 degradant, and can effectively inhibit the proliferation of tumor cells." (PMID 39697230, 2024). "In breast cancer, augmented levels of SMARCA4 enhance fatty acid synthesis through the transcriptional activation of lipogenic genes, such as ACC, FASN, and ACLY, facilitating rapid tumor growth through escalated DNL." (PMID 38374872, 2024). "However, in the presence of SMARCA4 and KRAS mutations, a shorter survival period was previously observed, which could be attributed to the lower PD‐1 expression and infiltration of CD8+ T cells in the tumor stroma." (PMID 39322625, 2024). "While the authors propose SMARCA4-deficient gastroesophageal carcinomas may not represent a unique tumor subtype, a more complete understanding of the full spectrum of SMARCA4 mutations will help define the patient population that may benefit from drug development." (PMID 38656564, 2024). "Mosaic expression for SMARCB1 (NKSCC—33%; KSCC—21.9%) and SMARCA4 (NKSCC—14.6%; KSCC—12.2%) was identified, showing an impact on tumor size and progression." (PMID 39590317, 2024).
tumor (continued). "Clinical NB cases with up‐regulation of KPNB1, CNBP, SMARCC1, SMARCA4 or down‐regulation of SMARCC2 have poor survival and prognosis, indicating KPNB1/CNBP/SMARCC2 axis as a valuable target for therapeutics of tumours." (PMID 37186134, 2023). "It has been reported that losses of SMARCA4 and SMARCA2, which play a role in the repair and remodeling of chromatin, contribute to the initiation, progression, and differentiation of neoplasms." (PMID 36178285, 2023). "In comparing gene expression profiles of our MYC/SMARCA4 tumors to an established SHH MB model, we identified upregulation of G protein signaling and glucose metabolism in our tumor model." (PMID 37919824, 2023). "First, for SMARCA4-WT CDX models, daily single treatment with either GSK-PTi or BBAi-1 had a moderate therapeutic effect, with a tumor growth inhibition (TGI) rate of 23% or 46.9%, respectively, in model mice." (PMID 36922568, 2023). "When A947 was administered in SMARCA4-mutant xenograft studies, tumour stasis was again observed despite >95% reduction of SMARCA2 levels in the tumours." (PMID 36720862, 2023). "SMARCA4 (BRG1) is the central ATPase of BAF complexes and has been identified as a major tumor suppressor." (PMID 37727504, 2023). "miR-199a-3p can induce metastasis of malignant tumor cells by inhibiting the expression of SMARCA2, downregulating the expression of SMARCA4, and inhibiting the expression of TGF-β." (PMID 35342417, 2022). "One tumor with acinar predominant histology and a missense SMARCA4 variant (patient Cd) and one with solid predominant histology and a combination of truncating and missense SMARCA4 variants (patient Ci) were TTF-1 negative, while the remaining tumors were TTF-1 positive." (PMID 35964518, 2022). "Both SMARCA4 and its paralog, SMARCA2, are identified as tumor suppressors or drivers of cancer and emerging therapeutic approaches are targeting these genes." (PMID 35626007, 2022). "Therefore, SMARCA4 may play an essential role in cancer prognosis and tumor immunity." (PMID 34675941, 2021). "AURKA has been identified as a synthetic lethal target for several tumor suppressors, including ARIDIA, SNF, and SMARCA4, as well as RB1." (PMID 34359608, 2021). "For example, high expression of SMARCD1, SMARCA4 and ARID1A can promote tumor cell proliferation and invasion, accompanied by poor survival." (PMID 34937564, 2021). "In particular, for each of the well-studied tumour suppressors ARID1A, SMARCA4 and PTEN the most significant robust synthetic lethal interaction we identified has previously been reported in the literature." (PMID 32463358, 2020). "Their study identified an unprecedented number of genes essential for tumor growth (e.g BAZ1B, SMARCA4, CHD4, KMT2D) and a certain interpatient heterogeneity." (PMID 32042336, 2020). "Other observations have shown that the effect of miR-21 on tumor invasion can also take place by inhibiting tumor suppressor genes ANP32A, SMARCA4 and sprouty homolog 2 (Spry2)." (PMID 32349263, 2020). "By analysing the expression of five subunits of the SWI/SNF complex (INI1/SMARCB1, SMARCA2, SMARCA4, ARID1A, PBRM1), we further explored the relevance of alterations in chromatin remodelling in glandular differentiated tumours." (PMID 32198650, 2020). "Exceptions included events private to the primary tumor (SETD2 and ARID1A in LUAD6; NOTCH2 in SCLC1), or private to metastases (SMARCA4 in LUAD5; ARID1A in LUAD7)." (PMID 30348992, 2019).
tumor (continued). "Tumor formation in Smarca4 heterozygous mice occurs with long latency and low penetrance, indicating that for treatment of SMARCA4-dependent cancers a therapeutic index for transient inhibition of SMARCA4 might exist without the risk of secondary malignancies." (PMID 31406271, 2019). "A second recent study confirmed and extended these findings, showing that about 80% of SCCOHT tumor samples exhibit strong EZH2 expression by immunohistochemistry; re-expression of SMARCA4 in these cells reduced EZH2 expression." (PMID 29389895, 2018). "In contrast to SMARCA4, SMARCA2 expression was strongly downregulated in most cancer types, which is consistent with a role as tumor suppressor of this protein." (PMID 29391527, 2018). "First we compared the levels of SMARCA4 and SMARCA2 transcripts in normal tissue with respect to tumor tissue in different types of tumors." (PMID 29391527, 2018). "Thus the tumor-promoting functions of SMARCA4 and SMARCA2 might be unique to ccRCC." (PMID 28445125, 2017). "Loss of SWI/SNF function has been associated with malignant transformation, and recent data demonstrate that several components of the SWI/SNF complexes, including ARID1A, ARID2, SMARCA4 (BRG1), SMARCB1 (SNF5), and PBRM1, function as tumor suppressors." (PMID 27351279, 2016). ", SMARCB1 and SMARCA4) as tumor repressors, emerging evidence suggests that SWI/SNF activity is essential for tumor initiation, maintenance and progression." (PMID 27495308, 2016). "SMARCA4, one of two SWI/SNF ATPase subunits, was first identified as a potential tumor suppressor in NSCLC, where expression is lost in 15%–50% of all tumors." (PMID 24622842, 2014). "Despite its context-dependent biological duality, SMARCA4 mutations exert a more pronounced negative effect on KRAS G12Ci efficacy and immunotherapy response compared to other frequently co-mutated tumor suppressors." (PMID 41541668, 2026). "However, in the case of tumor cell-induced CD4+ Tex, the replacement of SMARCA2 by SMARCA4 leads to increased CD274 expression." (PMID 40342423, 2025). "A recent investigation indicated that a low rate of immune checkpoint inhibitor response in SMARCA4-UT correlates with a lack of tumor-infiltrating lymphocytes within the tumor microenvironment." (PMID 41261718, 2025). "Studies have demonstrated that in patients with surgically resectable NSCLC, the loss of BRG1 protein and low levels of SMARCA4 expression predict a worse prognosis, irrespective of tumor stage." (PMID 41142791, 2025). "By IHC, the tumor demonstrated diffuse positivity to synaptophysin, PLAP negativity, retained INI-1, focally retained ATRX expression, and focally retained nuclear expression of SMARCA4." (PMID 41353556, 2025). "Tumor cells tested negative for SMARCA4 but were positive for Chromogranin-A(CgA), Synaptophysin (SYN), Insm-1, TTF-1 (partial), and Ki67 (90%)." (PMID 40661782, 2025). "Treatment approaches among SMARCA4-altered malignancies were notably heterogeneous, reflecting the diversity of tumor types and clinical presentations and the lack of standardized therapeutic guidance." (PMID 40867304, 2025). "The tumor cells showed a preserved expression of SMARCB1 (INI1) and SMARCA4." (PMID 40988318, 2025). "With the advancement of molecular techniques, the histologic diagnosis of AT/RT has been increasingly supported by methods such as next-generation sequencing, deletion/duplication analyses, and tumor microarray testing to detect and confirm SMARCB1 or SMARCA4 alterations." (PMID 41374972, 2025). "To validate whether our findings in cell line xenografts are representative of primary SMARCA4-UT tumors in patients, we initially made use of a YAP1 signature, previously used to interrogated YAP1 expression in SCLC Circulating Tumor Xenograft (CTX) models." (PMID 38180245, 2024). "Tumor cells were cohesive in the SMARCA4-dNSCLCs, whereas, tumor cells were poorly cohesive or noncohesive in the thoracic SMARCA4-UTs." (PMID 38374950, 2024).
tumor (continued). "The low expression of SMARCA4 might enhance the anti‐tumor immune response by regulating the TME, which could increase the infiltration of anti‐tumor immune cells, such as CD4+ T cells and CD8+ T cells." (PMID 39322625, 2024). "There are potential reasons why current treatments are not highly effective in treating SMARCA4/KRAS NSCLC co-mutations, as the tumor microenvironment (TME) plays an important role in metastatic NSCLC." (PMID 39063938, 2024). "The SMARCA4/SMARCA2 allosteric inhibitor, FHD-286, effectively suppressed the proliferation of a broad collection of patient-derived AML cells, promoted differentiation, and decreased tumor growth in vivo." (PMID 38390898, 2024). "SCRIPro could accurately predicts well-known master regulators including SPI1, IRF1, FLI1, and STAT2 for mono/macrophages, GATA3, RUNX3, SMARCA4, JUND, and MYB for T-cells, PAX5, BCL2, and IRF4 for B and tumor B-cells." (PMID 39024032, 2024). "Unfortunately, there is no way to protect the child from developing a tumor if genetic changes have occurred in the SMARCA4 gene." (PMID 40729139, 2024). "Pathology of the small bowel lesion revealed rhabdoid features, and the tumor cells were negative for SMARCA4 staining." (PMID 39360100, 2024). "Moreover, the bias of ARID1A and SMARCA4 in different tumors and their pro- or anti-cancer effects in different tumors and different processes of tumor development have led to the incomplete study of ARID1A and SMARCA4 at present." (PMID 39697230, 2024). "BRG1 inhibition has been observed to prevent panIN formation and block panIN-derived PDAs by inducing apoptosis.SMARCA4 binds to the SOX9 promoter and helps to initiate the transcription of SOX9.SOX9 has been shown to affect tumor proliferation, and SOX9 knockdown has a pro-apoptotic effect." (PMID 39697230, 2024). "SMARCA4 expression was positively correlated with multiple NE genes including SYP, CHGA, INSM1, DLL3 and NCAM1 and negatively correlated with non-NE factors REST, NOTCH2, and YAP1 in both SCLC cell lines and patient tumor databases." (PMID 39080761, 2024). "Bioinformatic study showed that tumor stem cells activated TCF3, SMARCA4, TFF3, etc.." (PMID 37717019, 2023). "SMARCA4, one of the subunits of the SWI/SNF chromatin remodeling complex, is a tumor suppressor." (PMID 38090508, 2023). "Unlike SMARCA4, its paralog SMARCA2 is not frequently mutated in cancers but rather is epigenetically silenced across numerous tumor types and cancer cell lines." (PMID 37093326, 2023). "For the 12 tumours with high signature 27 exposure but no biallelic LOF mutations, we did not observe a similar decrease in expression, suggesting that SMARCA4 was not epigenetically silenced or otherwise transcriptionally inactivated in these cases." (PMID 36883553, 2023). "In addition, SMARCA4 upregulate expression led to increased migration and invasion of OSCC cells in vitro, as well as tumor growth and invasion in vivo." (PMID 36902184, 2023). "Multiple studies have reported that ATRT patients who retained positive nuclear staining for SMARCB1 in tumour cells lacked staining for SMARCA4." (PMID 37433987, 2023). "In contrast to this tumor suppressor role, gain-of-function of ARID1A and SMARCA4 was found in hepatocellular carcinoma and in breast cancer, respectively, suggesting that SWI/SNFc alterations could also act as oncogenes." (PMID 37446319, 2023). "SMARCA4 generally appears to play a tumour suppressor role in MB and ATRT as opposed to having the function of an oncogene in GBM." (PMID 37433987, 2023). "As expected, we also detected lower protein levels of EGFR and TNS4 in tumor tissues of SMARCA4-R1157W mutant CDX models after treatment with GSK-PTi and BBAi-1 by western blot and IHC analysis than those in SMARCA4-WT CDX models." (PMID 36922568, 2023).
tumor (continued). "Our results not only confirm known associations, such as mismatch repair and POLE gene mutations with high TMB, but also identify significant associations between mutations in the SWI/SNF chromatin remodelling genes ARID1A and SMARCA4 and high TMB in multiple tumour types." (PMID 37821580, 2023). "Overall, the consensus of the literature is that SMARCA4 supports SHH MB, therefore selective and timely inhibition of SMARCA4 could be a potential therapeutic strategy to treat this tumour type." (PMID 37433987, 2023). "Since tumor invasion and metastasis are closely related to OSCC progression, we examined whether SMARCA4 is involved in OSCC cell migration and invasion." (PMID 36902184, 2023). "Although SMARCA4 loss or MYC overexpression did not increase proliferation of GCPs in vitro, the combination of both alterations induced tumor formation after orthotopic transplantation in vivo." (PMID 37919824, 2023). "As a clear driver for the NEC-like SMARCA4/ARID1A molecular tumor class was not apparent in the available retrospective data, we performed whole exome (n = 9) or NGS panel sequencing (n = 10) of 19 tumors from this group." (PMID 36443295, 2022). "SMARCA4, which encodes a fundamental unit of SWI/SNF (switch/sucrose non-fermentable) chromatin remodeling complex, acts as a tumor suppressor but is frequently inactivated by mutations in non-small cell lung cancer (NSCLC)." (PMID 36110953, 2022). "These tumor cells were negative for SMARCA4, p40, NUT, and claudin-4, leading to establishing a diagnosis of thoracic SMARCA4-deficient undifferentiated malignancy." (PMID 35778998, 2022). "Immunohistochemically, the tumor cells totally lacked SMARCA4 and BRM (SMARCA2); were negative for TTF1, AE1/3, Claudin4, desmin, MyoD1, myogenin, CD99, CD56, and WT‐1 proteins; and were weakly positive for synaptophysin." (PMID 36523385, 2022). "The role of SMARCA4 in promoting melanin synthesis likely provides protection against damage from UVR and could be considered a tumor suppressor role." (PMID 35323214, 2022). "Therefore, SMARCA4-DTS is difficult to diagnose, with differentiation points including the loose binding of tumor cells, formation of glandular cavities and papillary growth, and strong diffuse staining of pan-keratin." (PMID 35151345, 2022). "Several subunits of the SWI/SNF complex including SNF5 (SMARCB1/INI1/BAF47), ARID1A (BAF240A), SMARCA4 (BRG1), ARID1B (BAF250B), ARID2 (BAF200) and PBRM1 (BAF180) exert critical tumor suppression activities, through inhibiting oncogenic transcription, cell cycle, epigenetic instability and etc.." (PMID 33670012, 2021). "It has been established that SMARCA4-dNSCLC is independently a highly aggressive tumor with poor patient survival outcome, regardless of the TNM stage." (PMID 34440689, 2021). "However, SMARCA4 also has tumor suppressor activities in solid tumors, similarly to SMARCA2, which is generally classified as a tumor suppressor." (PMID 34298819, 2021). "The expression difference, mutation and phosphorylation status, survival, pathological stage, DNA methylation, tumor mutation burden (TMB), microsatellite instability (MSI), mismatch repair (MMR), tumor microenvironment (TME), and immune cell infiltration related to SMARCA4 were analyzed." (PMID 34675941, 2021). "The model developed here combines clinical variables available preoperatively (tumor morphologic appearance on CT, tumor SUVmax, and clinical stage) and genomic data (SMAD4 and SMARCA4 alterations) that can be obtained from a preoperative biopsy specimen to better guide the therapeutic strategy." (PMID 34290393, 2021).